MALAT1 (metastasis associated lung adenocarcinoma transcript 1)
Diseases named in the same sentence as MALAT1 in open-access papers (continued):
Sharing a sentence is not in itself a finding about the gene and the disease.
tumor (continued). "Similarly, the miR-107/LAST2 axis is regulated by the m6A “eraser” ALKBH5 in an HuR-dependent manner to decrease YAP activity and inhibit tumour growth; lncRNA MALAT1 is stabilized by the METTL3/YTHDF1 complex and its RNA level is increased with high levels of m6A modification." (PMID 35004679, 2021). "In addition, MALAT1 depletion restrained xenograft tumor growth in vivo." (PMID 34222668, 2021). "Moreover, MALAT1 knockdown suppressed tumor growth in Ox-treated nude mice." (PMID 33005106, 2020). "However, MALAT1 might regulate signaling pathway downstream of type I IFN, because a study showed that silencing MALAT1 attenuated the activation of the JAK/STAT pathway in a tumor cell." (PMID 32321151, 2020). "Interestingly, the NHBE cells showed overexpression of the lncRNA metastasis-associated lung adenocarcinoma transcript 1 (MALAT1), which is also known to be overexpressed in multiple neoplastic diseases, as well as inflammatory processes after lung transplants." (PMID 33271762, 2020). "Besides, knockdown of MALAT1 inhibited tumor growth in vivo through miR‐185‐5p/MDM4 axis in NSCLC." (PMID 33146951, 2020). "Also, the effect of MALAT1 on tumor growth was detected in xenograft tumor mice treated with Ox." (PMID 33005106, 2020). "MALAT1 is subjected to elevated mutational rates in human tumours, although it has not yet been established whether these mutations drive tumorigenesis." (PMID 32024996, 2020). "Thus, the target miRNAs of MALAT1 are expected to be tumor suppressive." (PMID 32728178, 2020). "Moreover, MALAT1 silencing repressed tumor growth in Ox-treated nude mice." (PMID 33005106, 2020). "LncRNA Metastasis Associated Lung Adenocarcinoma Transcript 1 (MALAT1) can bind to RBP HuR, and this MALAT1/HuR complex can interact with the 3′ UTR of T cell intracellular antigen (TIA-1) mRNA and inhibit its translation, resulting in stimulation of autophagy in tumor cells." (PMID 32973402, 2020). "In the current study, we demonstrate that the EWS-FLI1 oncoprotein, which is characteristic of ES, enhances TNC expression by directly binding to its promoter region and that integrin α5β1-mediated YAP activation may be responsible for MALAT1 upregulation in TNC-induced ES tumour progression." (PMID 31649319, 2019). "Therefore, the foremost cause of the discrepancy may be due to the tumor microenvironment (TME) and metabolism of lncRNA in vivo, and clearly further work needs to be performed to establish whether MALAT1 does have dual effects in BC." (PMID 31744046, 2019). "Moreover, a luciferase xenograft mouse model was established to determine whether MALAT1 expression affects tumor metastasis in vivo." (PMID 30771618, 2019). "Thus, MALAT1 is probably involved in tumor development and could be a new biomarker for predicting tumor recurrence after LT." (PMID 31341758, 2019). "Moreover, accumulating evidence indicated that expression levels of MALAT1 in tumor tissues and/or body fluids could serve as a biomarker for tumor diagnosis and prognosis." (PMID 31500187, 2019). "The knockdown of MALAT1 could partly imitate the tumor-inhibitive impact of miR-1." (PMID 31214490, 2019). "Additionally, MALAT1 levels are a valuable prognostic for patient survival in tumours of the lung." (PMID 31382922, 2019). "In addition, MALAT-1 is overexpressed in different types of tumors, such as lung cancer, pancreatic cancer, breast cancer and colorectal cancer, and can influence the prognosis of tumor patients by promoting tumor growth, invasion and metastasis." (PMID 31632488, 2019). "Importantly, MALAT1 overexpression promoted tumor growth when compared with the vector control." (PMID 30683916, 2019). "Finally, we proved that MALAT1 promoted OS tumor growth in an in vivo animal study." (PMID 30094957, 2018). "In addition to directly enhancing its own proliferation and migration abilities, MALAT1 could affect interactions between tumor cells and host immune environment." (PMID 29416769, 2018).
tumor (continued). "Similarly, lncRNAs HOTAIR and MALAT1 are upregulated in endothelial-derived exosomes by ethanol, which might have implications for alcohol-induced tumor angiogenesis." (PMID 29678180, 2018). "However, it is unclear whether the effect of MALAT1 on SOX2 in these tumor cells is direct or indirect." (PMID 28388544, 2017). "In addition, recent studies suggest that MALAT1 may act as a competing endogenous RNA (ceRNA) by binding to tumor-suppressive miRNAs." (PMID 28350340, 2017). "MALAT1 (metastasis-associated lung adenocarcinoma transcript 1) is one of the most studied and abundant lncRNAs: its expression was initially associated with metastasis in non-small-cell lung carcinoma (NSCLC), but then its deregulation has been reported in several other neoplastic diseases." (PMID 29147648, 2017). "Furthermore, the functional role of MALAT1 in the regulation of cell proliferation, apoptosis and metastasis suggested that MALAT1 may play a key role in tumor progression." (PMID 27777857, 2016). "In addition, knocking down MALAT-1 with targeted siRNAs could decrease the migration and invasion of tumor cells in vitro." (PMID 26989678, 2016). "Furthermore, hypoxic upregulation of MALAT1 in endothelial cells contributes to the angiogenic response, indicating that MALAT1 may play an important role in tumor angiogenesis." (PMID 26590207, 2016). "As a tumor promoter, MALAT-1 could be transcriptionally activated by c-Fos and could interact with Ezh2, silencing the tumor suppressor gene E-cadherin and upregulating β-catenin expression that induce tumor promotion in RCC." (PMID 27806310, 2016). "Similarly, diminished MALAT1 expression impaired tumor formation and growth in nude mice." (PMID 27686732, 2016). "On the contrary, enhanced expression of MALAT-1 could promote tumor cell matrigel invasion." (PMID 26989678, 2016). "Finally, we determined whether the MALAT1 amplification in tumor tissues was derived from germline origins." (PMID 25613496, 2015). "MALAT1 inhibition may elicit an antiangiogenic effect in the hypoxic tumor environment." (PMID 26420912, 2015). "Therefore, MALAT1 may play an important role in tumor progression and could be a novel biomarker for predicting tumor prognosis." (PMID 26136615, 2015). "Based on our results, we propose that abnormal expression of MALAT1 in specific cell types or tissues results in aberrant alternative splicing leading to misexpression of genes that are involved in cell cycle progression and/or cell death, thereby contributing to tumor progression." (PMID 23555285, 2013). "Thus, it would be reasonable to analyze MALAT1 in plasma of NSCLC patients instead of the cellular fraction, because the presence of MALAT1 in plasma might be a direct effect of the tumor, e.g., release of lncRNA-containing extracellular vesicles." (PMID 24313945, 2013). "This study aimed to compare the expression of exosomal HOTAIR, NEAT1, MALAT1, AFAP1-AS1, ANRIL, and HULC lncRNAs in primary tumor tissue and blood of patients with sporadic TNBC to evaluate their potential as biomarkers." (PMID 42196289, 2026). "MALAT1, on the other hand, plays multiple roles in CRPC, including tumor aggressiveness, castration resistance, and poor clinical outcomes." (PMID 41294881, 2025). "LncRNA MALAT1 and HOTAIR are highly expressed in LUAD, promoting tumor cell proliferation, and inhibiting apoptosis by regulating cell cycle proteins and apoptosis-related molecules (such as BCL-2 and BAX)." (PMID 39834603, 2025). "Administering a large dose of unlabeled MALAT1 ASO before the labeled probe prevented its binding to MALAT1, resulting in a significant decrease in fluorescence intensity in the tumor region." (PMID 40597438, 2025). "Further, MALAT-1 is also emerging as a new potential therapeutic target for CRPC since it is correlated with high Gleason score, prostate-specific antigen, and tumor stage." (PMID 41303378, 2025).
tumor (continued). "The positive control, compound 5, reduced MALAT1 levels by 50%, as observed previously in MMTV-PyMT tumor organoids, and had a similar effect on lowering premature-only MALAT1." (PMID 41226238, 2025). "MALAT1 can interact with the histone methyltransferase EZH2, leading to the enrichment of EZH2 in certain tumor suppressor gene promoter regions and catalyzing the trimethylation of H3K27me3." (PMID 41394878, 2025). "This study is the first to confirm that MALAT1 upregulates PRKAG1 expression by sponging miR-383-5p to promote HCC, consistent with the tumor-suppressive role of miR-383-5p." (PMID 40958861, 2025). "TGF-β induces the expression of lncRNA MALAT-1 in HNSCC cells, and it promotes invasion, migration, and tumor growth by sponging miR-30a15." (PMID 40594481, 2025). "The research revealed a significant upregulation of MALAT1 expression in A431, PC9GR, A549, and PC9 tumor cell lines relative to the HUVEC cell line, with PC9 exhibiting the highest expression and A431 the lowest." (PMID 40597438, 2025). "lncRNAs, such as HOTAIR and MALAT1, upregulate BCL-2 via epigenetic and ceRNA mechanisms, promoting tumor survival." (PMID 41020820, 2025). "SNHG6 was expressed at the tumor edge and in the pseudopalisading regions around necrosis, but most lncRNAs (Pvt1, SNHG12, H19, Neat1, Malat1, Mir17hg and Ftx) were expressed around the necrotic tumor regions." (PMID 40527978, 2025). "PRKAG1, as a downstream target of MALAT1, was also highly expressed in HCC and correlated with tumor stage and adverse outcomes." (PMID 40958861, 2025). "This process is mediated through the MALAT1/miR‐143‐3p/RRM2 axis, wherein resveratrol downregulates the oncogenic lncRNA MALAT1, upregulates miR‐143‐3p, and inhibits the expression of RRM2, a known promoter of tumor progression." (PMID 40708783, 2025). "LINC01133, like other lncRNAs of interest, such as HOTAIR, MALAT1, TUG1, and FOXCUT, should be at the forefront of clinical research, considering its importance both in the intratumoral context and in the tumor microenvironment." (PMID 40863724, 2025). "This study elucidates the oncogenic role of the MALAT1/miR-383-5p/PRKAG1 axis in HCC, demonstrating that PRKAG1 promotes tumor progression by regulating cell proliferation, the immune microenvironment, and key signaling pathways." (PMID 40958861, 2025). "Knockdown of MALAT1 effectively inhibits TGFβ1-induced EMT, highlighting its role as a downstream effector of TGFβ-mediated tumor progression." (PMID 41437175, 2025). "Some lncRNAs, including 91 H, BCAR4 and MALAT-1, are overexpressed, exhibiting oncogenic features, whereas others like Loc285194 and MEG3 are downregulated and serve tumor suppressive roles." (PMID 40868849, 2025). "A number of lncRNAs discussed in previous sections, such as SNHG17, MALAT1, XIST, SBF2-AS1, NKILA, and Linc-pint, have been shown to regulate tumor behavior in preclinical studies through their interaction with the TGFβ pathway." (PMID 41437175, 2025). "MALAT1, one of the earliest identified dysregulated lncRNAs in NSCLC, is highly expressed in most tumor tissues." (PMID 39895777, 2025). "The pretreatment tumor tissue lncRNAs OIP5, CCAT1, UCA1, and MALAT1 were overexpressed (value more than 1) in 69.29%, 70.73%, 31.70%, and 36.58% samples, respectively, as compared to the control value (value =1) derived from normal mucosal samples of patients." (PMID 40568293, 2025). "MALAT1 was found to sponge miR-195 and increase PD-L1 expression in DLBCL patient samples and a derived cell line, promoting tumor proliferation and immune escape." (PMID 40733622, 2025). "hsa-miR-378a-3p also exacerbated significant modulatory and silencing effects on the expression of MALAT1 and NEAT1, which are well known to influence tumor progression and inflammatory processes through the propagation of the NF-κB pathway." (PMID 41226545, 2025).
tumor (continued). "MALAT1 exerts its effects by interacting with critical signalling pathways, notably PI3K/Akt and Wnt/β‐catenin, and by acting as a molecular sponge for tumour‐suppressive microRNAs." (PMID 41261348, 2025). "In the TCGA-COAD (GA) dataset, there were 33 patients whose tumor tissues simultaneously expressed higher levels of TCF12 mRNA, MALAT1, and β-catenin mRNA." (PMID 39768127, 2024). "For instance, maternally expressed gene 3 functions as a tumor suppressor, whilst HOX transcript antisense intergenic RNA and MALAT1 have significant oncogenic impacts." (PMID 39471147, 2024). "Numerous lncRNAs and their sponged targets have been identified as both diagnostic and therapeutic targets in the development of GBM tumours, such as LINC02015, H19, KIAA0495, AC068888.1 and MALAT1." (PMID 38594690, 2024). "For example, the suppression of specific lncRNAs like MALAT1 and HOTAIR has shown to inhibit tumor growth and metastasis in animal models." (PMID 39512820, 2024). "It was demonstrated that YAP protein induces MALAT1 transcription through the TCF/β-catenin element located in the MALAT1 promoter region, which leads to tumor growth." (PMID 38226210, 2024). "MALAT1 is known to bind to EZH2 and direct it to specific chromatin regions, leading to tumor suppressor gene repression, it can activate the EZH2-Notch1 and the PI3K/Akt signaling pathways." (PMID 38672463, 2024). "The synthesis of inflammatory cytokines is seen to be inhibited by the MALAT-1-mediated release of FGF2 from TAMs, but tumor cell growth, migration, invasion, and the development of angiogenesis are promoted." (PMID 38511067, 2024). "The volume and weight of tumor growth in nude mice in PC9ER and PC9 + MALAT-1 groups were larger than those in their parents and control groups." (PMID 39196297, 2024). "Based on previous studies, some lncRNAs have been assigned as oncogenic (MALAT1, PCA3, HOTAIR, H19, PARTICLE, etc.)or as tumour suppressors (GAS5, MEG3, TERRA, etc.)." (PMID 38790894, 2024). "In contrast, lncRNAs such as ANCR, MALAT1, and NKILA have been demonstrated to inhibit tumor growth and attenuate the invasive spreading and metastasis of BC." (PMID 39795985, 2024). "We have also developed a model for a TFEB translocation, MALAT1-TFEB, where TG lines were created from both the primary tumor and a lymph node metastasis." (PMID 38386415, 2024). "For example, the lncRNA MALAT1 induces tumor cell proliferation and metastasis by regulating downstream genes in LUAD, and the lncRNA HOTAIR induces tumor cell proliferation and invasion by regulating downstream genes in LUAD." (PMID 38355480, 2024). "The MALAT1-regulated TIME can facilitate the breakdown of cell–cell adhesion, and enhances migratory properties, all of which collectively contribute to tumor growth and metastatic dissemination." (PMID 38791954, 2024). "It discusses the impact of MALAT-1 on immunomodulatory molecules, such as major histocompatibility complex (MHC) proteins and PD-L1, leading to immune evasion and hindering anti-tumor immune responses." (PMID 38511067, 2024). "Considering the role of WTAP in tumor progression, we decided to perform a wound-healing migration assay upon silencing of WTAP and MALAT1 in hypoxic condition." (PMID 38862471, 2024). "For instance, tumor-suppressor miRNAs such as and miR-199b-3p, miR-129-3p, miR-490-3p, and miR-26a-5p directly repress AURKA, whereas lncRNAs like MALAT1 and TUG1 indirectly upregulate AURKA by sponging and downregulating tumor-suppressor miRNAs." (PMID 39598228, 2024). "For example, the lncRNA MALAT1 and HOTAIR were overexpressed in ESCC tumor tissues and served as good predictive factors for overall survival." (PMID 38457049, 2024). "MALAT-1 modulates EMT by sponging miR-142-3p, resulting in the upregulation of SMAD5 expression and subsequently activating tumor invasion and metastasis." (PMID 38201661, 2024).
tumor (continued). "They explored the role of MALAT-1 lncRNA in HCC and found that, in contrast to healthy liver controls, it was highly expressed in HCC tumor tissues." (PMID 38511067, 2024). "In the orthotopic GBM mouse model, tumor inhibition and prolonged life survival were achieved with concurrent treatment of TMZ and nanocomplex-mediated silencing of MALAT1." (PMID 38675144, 2024). "In vivo studies, knockdown of the lncRNAs MALAT-1, HULC, DANCR, and AP000695.2 revealed inhibition of tumor cell growth." (PMID 39346921, 2024). "This microRNA can regulate the expression of MALAT1 and has been found to impede MALTA1-mediated proliferation, tumor growth, and metastasis." (PMID 38140218, 2023). "Antisense oligonucleotides of MALAT1 and HOTAIR have shown effective tumor‐inhibiting power in preclinical models." (PMID 36992525, 2023). "In summary, in order to translate our results into clinical practice, we have shown that MALAT1, MANCR and miR-101 hold promise as potential prognostic indicators for EAC patients, depicting worse survival and worse tumor staging when dysregulated." (PMID 38203269, 2023). "Cell cultures of triple-negativebreast cancer (MDA-MB-231, primary TNBC cells, Hs578T, and HCC1806) werecharacterized by lower MALAT1 levels compared to ER+ cells (MCF-7, primary ER+tumor cells, and T-47D)." (PMID 37538803, 2023). "Subsequently, to examine the coinhibitory potential of MALAT1 and PARP1 in distant tumor metastasis, we determined the levels of human-specific Alu sequences in the lungs and bone marrow collected from xenografted mice." (PMID 37812088, 2023). "Particularly, coinhibition of MALAT1 and PARP1 exhibits a decline in clonogenic survival, delays resolution of γH2AX foci, and reduces tumor burden in mice xenograft model." (PMID 37812088, 2023). "Tang et al26 found that MALAT‐1 and HOTAIR are expressed in patients with primary OSCC tumors; the expression level of HOTAIR differed between patients with LNM and primary tumor controls." (PMID 37635388, 2023). "Administration of MALAT1 siRNAand/or ASC-J9 (5-hydroxy-1,7- bis(3,4-dimethoxyphenyl)-1,4,6-heptatrien-3-one)suppressed the progression of EnzR-PCa tumor cells." (PMID 37538803, 2023). "It has also been reported that MALAT-1 expression closely correlates with PSA levels, Gleason scores, and tumor sizes." (PMID 37218885, 2023). "The results of differential expression analysis of MALAT1 and TOP2A in BC showed that the expression of MALAT1 and TOP2A in tumor tissues increased significantly in patients' tissues compared to normal tissues." (PMID 37244966, 2023). "Up-regulated tumor-promoting lncRNAs such as MALAT1, UCA1, H19, HIF1A-AS2 and down-regulated tumor suppressor lncRNAs such as NBAT1, GASS, RNCR3, etc., all of which play an important role in the formation and malignant progression of gliomas." (PMID 37153654, 2023). "The expression level of onco-lncRNAs, including PCAT19, MALAT1, and NEAT1, and the tumor suppressor lncRNA, CASC2, was increased and decreased, respectively, in PCa patients compared to the healthy group (P < 0.05)." (PMID 37251950, 2023). "MALAT-1 can facilitate epithelial-mesenchymal transition (EMT) in RCC, leading to increased tumor aggressiveness and metastatic potential." (PMID 38124072, 2023). "In colorectal cancer, the binding of MALAT1 to SFPQ releases the PTBP2 oncogene from an SFPQ/PTBP2 complex, which promotes tumor growth and metastasis." (PMID 37444543, 2023). "Subsequently, Zhang and colleagues discovered that exosomal MALAT1 was substantially abundant in the serum of NSCLC patients, which sped up tumor migration and proliferation by inhibiting cell apoptosis and shortening cell cycle." (PMID 36362424, 2022). "S8, G to I), indicating that stable knockdown of MALAT1, PTBP1, and PSF effectively inhibited tumor growth in vivo." (PMID 36563164, 2022).